BMI1 (BMI1 proto-oncogene, polycomb ring finger)
Diseases named in the same sentence as BMI1 in open-access papers (continued):
Sharing a sentence is not in itself a finding about the gene and the disease.
melanoma (continued). "miR-200c has been proposed to prevent the establishment of drug resistance in melanoma by targeting Bmi-1, Zeb2, Tubb3, ABCG5, and MDR1, transcriptional repressors that belong to a complex signaling network involved in the epithelial to mesenchymal transition (EMT)." (PMID 32054078, 2020). "In melanoma, miR‐203 is downregulated and consequently its target BMI1 is upregulated." (PMID 30499222, 2019). "In SKMEL28 melanoma cells, only Sox2 and Bmi1 showed a 2-fold upregulation when treated with bFGF." (PMID 30675361, 2019). "Moreover, PCR1 component BMI1 was shown to contribute to the induction of melanoma gene signatures correlating with metastasis as well as chemo-resistance to BRAF-inhibitors." (PMID 28978033, 2017). "Although an association between Bmi-1 mRNA and miR-200c has not elucidated, the effects of miR-200c on melanoma cell proliferation, migration, and resistance to cisplatin were rescued by overexpression of Bmi-1." (PMID 23965981, 2013). "Furthermore, metastatic melanoma tissues and cell lines show much higher expression of Bmi-1 than primary melanoma tissues and cell lines." (PMID 21276221, 2011). "Also, it has been shown that Bmi-1 mediated repression of p16 can lead to increased aggressive behavior of melanoma stem cells." (PMID 20574517, 2010). "Thus, RT-PCR was used in a complex molecular approach for demonstrating the downregulation of miR-29 in an A375 melanoma cell line; miR-29a could potentially suppress melanoma by negatively regulating apoptosis-related protein Bmi1." (PMID 32185171, 2020). "TCGA dataset revealed that TIPE has a positive relationship with CSCs markers, including BMI1, NANOG, NOTCH1, and POU5F1 in melanoma." (PMID 39728923, 2024). "Lastly, TCGA dataset revealed that TIPE has a positive relationship with CSCs markers including BMI1, NANOG, NOTCH1, and POU5F1 in melanoma." (PMID 39728923, 2024). "BMI1 overexpression induced resistance in melanoma cells sensitive to pharmacological BRAFV600E inhibition, while BMI1 silencing increased BRAFi sensitivity proportional to the degree of knockdown." (PMID 36497341, 2022). "When tiers three and four are grouped together, such that the results from liver, stomach, renal, pancreatic, urothelial cancers, lymphoma and melanoma are pooled, there is also a strong inverse correlation between YY1 and BMI1 expressions (R2 = −0.7)." (PMID 27225481, 2016). "This strongly indicates that endogenous SSX2 indeed inhibits BMI1 PcG body formation and repressive function in FM45 melanoma cells." (PMID 25249625, 2014). "Several markers of melanoma stem cells have been described in recent studies including CD133, CD166, Nestin and BMI-1." (PMID 22275987, 2008). "Differential BMI1, TWIST1, and SNAI2 mRNA expression patterns correlate with malignancy type in a spectrum of common cutaneous malignancies, including basal cell carcinoma, squamous cell carcinoma, and melanoma." (PMID 40332096, 2025). "Additionally, mir-16 directly targets oncogenes like BMI1 and EZH2, promoting melanoma development and metastasis." (PMID 39061157, 2024). "The induction of the noncanonical Wnt pathway by BMI1 was also observed in melanoma cells that were resistant to the treatment of BRAF inhibitor by the upregulation of the Wnt5a and ROR2 receptors." (PMID 32726929, 2020). "Basic Fibroblast Growth Factor also induced Bmi1 in C139N similar to melanoma cells but not in the others." (PMID 30675361, 2019). "Their studies show that miR-218 plays a pivotal role in the development of the disease and by targeting CIP2A and BMI1, miR-218 regulates the proliferation, migration and invasion of the melanoma cell lines A375 and SK-MEL-2, explaining miR-218's pivotal role in melanoma development." (PMID 25015035, 2014).
melanoma (continued). "To investigate whether the SSX2-mediated disintegration of BMI1 and EZH2 nuclear bodies in A375 melanoma cells influenced the repressive function of these proteins, we performed global gene expression profiling of A375 cells with and without ectopic SSX2 expression." (PMID 25249625, 2014). "Additionally, BMI1 epigenetic regulation demonstrates that melanoma cell states are not as binary (invasive or proliferative) as typically described; paradoxical epigenomic states exist which enable MITF alterations without proliferation changes or shifts in therapeutic BRAFi sensitivity." (PMID 36497341, 2022). "Since FM45 melanoma cells are SSX2/3-positive and do not contain BMI1 PcG bodies, we investigated whether SSX2 is, in fact, responsible for the absence of BMI1 bodies in these cells." (PMID 25249625, 2014). "However, there are also differences in the function of SSX2 and SYT-SSX2 in that only the latter has been shown to destabilize and reduce the overall levels of BMI1 in sarcoma cells, an effect not observed with SSX2 in melanoma cells." (PMID 25249625, 2014).
nasopharyngeal carcinoma (41 papers, 2008 to 2025). A carcinoma arising from the nasopharyngeal epithelium. "Upregulation of BMI‐1 was associated with the invasion of nasopharyngeal carcinomas and predicted poor survival." (PMID 34859959, 2022). "In contrast, up-regulation of Bmi-1 was shown to be associated with the invasion of nasopharyngeal carcinomas and to predict poor survival." (PMID 21276221, 2011). "It has been reported that miR-320a inhibits cell proliferation, migration, and invasion by targeting the BMI-1 gene in nasopharyngeal carcinoma, and may be implicated in the α-synuclein aggravation in Parkinson's disease." (PMID 28910318, 2017). "We previously reported the oncogenic function and the transcription regulation mechanisms of Bmi1 in nasopharyngeal carcinoma (NPC)." (PMID 33014838, 2020). "CD24high human nasopharyngeal carcinoma cells express stem cell genes (Sox2, Oct4, Nanog, and Bmi-1) with Wnt/β-catenin signaling activation." (PMID 30467381, 2019). "Bmi1 can also indirectly repress E-cadherin expression by activating Snail in breast and nasopharyngeal cancer." (PMID 26023734, 2015). "Overexpression of Bmi-1 is common in many types of human cancer, including nasopharyngeal carcinoma." (PMID 24167620, 2013). "It has been reported that Bmi-1 induces epithelial-mesenchymal transition (EMT) in nasopharyngeal carcinoma cells through stabilizing Snail, a transcriptional repressor associated with EMT, via modulation of the PI-3K/Akt/GSK-3β pathway." (PMID 23383216, 2013). "It has been reported that knockdown of BMI-1 makes nasopharyngeal carcinoma cells more sensitive to 5-FU treatment and that depletion of BMI-1 enhances 5-FU-induced apoptosis." (PMID 21311599, 2011). "Consistent with a recent report, which showed that Bmi-1 autoantibodies in sera were a potential new biomarker of nasopharyngeal carcinoma, our results showed that Bmi-1 autoantibodies were presented in a subgroup of ESCC sera." (PMID 20809956, 2010). "A recent report has shown that Bmi-1 autoantibodies were newly potential biomarkers of nasopharyngeal cancer." (PMID 20809956, 2010). "We found that Bmi-1 mRNA levels were elevated in nasopharyngeal carcinoma (NPC) cell lines." (PMID 37219449, 2023). "In nasopharyngeal carcinoma cells, silencing Bmi-1 resulted in a reversal of EMT, exhibited by a shift in epithelial and mesenchymal markers and a reduction in metastases, indicating that Bmi-1 induces EMT resulting in a more migratory and aggressive phenotype in vitro." (PMID 36726797, 2023). "c-Myc regulates BMI1 expression in nasopharyngeal carcinoma." (PMID 36362068, 2022). "Previous studies have shown that Bmi-1 may directly bind to PTEN promoter in nasopharyngeal carcinoma cells." (PMID 27644439, 2016). "Previous studies have also shown that Bmi-1 may inhibit the expression of PTEN by direct binding to the PTEN promoter in nasopharyngeal carcinoma cells." (PMID 27644439, 2016). "However, BMI-1 autoantibody as a biomarker has seldom been studied with the exception of nasopharyngeal carcinoma." (PMID 22132147, 2011). "In our previous investigation, however, we found that Bmi-1 may promote immortalization of nasopharyngeal carcinoma by modulating the expression of other genes, besides regulating p16Ink4a." (PMID 20377880, 2010). "For example, elevated Bmi-1 levels were observed in 38.7% (29/ 75) cases in nasopharyngeal carcinoma, and its overexpression is correlated to the patients’ survival rate: the 5-year overall survival rate was higher in the Bmi-1-negative group than that in the Bmi-1-positive group (84.2% vs.47.6%)." (PMID 28122538, 2017). "We previously reported that Sp1 activates the transcription of Bmi1 and CENPH in nasopharyngeal carcinoma." (PMID 25099028, 2014).
nasopharyngeal carcinoma (continued). "A study has shown that BMI1 inhibited the expression of PTEN, and modulated PI3K/AKT/GSK-3b/snail signaling, which promotes EMT and enhances the metastatic ability of nasopharyngeal cancer cells." (PMID 23820733, 2013). "In addition, it has been found that Bmi-1 is overexpressed in a variety of human cancers, such as mantle cell lymphomas, non-small cell lung cancer, B-cell non-Hodgkin's lymphoma, breast cancer, colorectal cancer, prostate cancer, nasopharyngeal carcinoma and gastric carcinoma." (PMID 20809956, 2010). "Compared with nasopharyngeal carcinoma cell lines, NPEC2 Bmi-1 cell line as a control may be feasible." (PMID 22321704, 2012). "Upregulation of Bmi-1 also induces the epithelial-mesenchymal transition (EMT), enhances the aggressiveness of human nasopharyngeal carcinoma cells and stabilizes Snail, a transcriptional repressor associated with EMT, via modulation of the PI3K/Akt/GSK-3β pathway." (PMID 22967049, 2012). "The most differentially expressed genes in the main ceRNA network were chosen for nasopharyngeal carcinoma (NPC) cell lines and NPEC2 Bmi-1 cell line verification." (PMID 32095369, 2020). "Bmi-1 overexpression can promote epithelial-mesenchymal transition (EMT) in NPECs, whereas Bmi-1 knockdown can reverse EMT and reduce the metastasis of nasopharyngeal carcinoma cells (NPC)." (PMID 21276221, 2011). "The apparent difference between the role of Bmi-1 in reported nasopharyngeal carcinoma cases and our material of OSSC may also be explained by the fact that nasopharyngeal carcinoma is a non-keratinising type of carcinoma." (PMID 20145620, 2010).
hepatocellular carcinoma (38 papers, 2006 to 2025). A malignant tumor that arises from hepatocytes. "We used SEREX technology to identify novel tumour-associated antigens in patients with primary hepatocellular carcinoma and found serological responses to the polycomb group (PcG) protein BMI-1, which is overexpressed in a range of different tumour types." (PMID 17024127, 2006). "In addition, in vivo studies reported the upregulation of BMI1 in cancer tissues and are associated with remote metastases of gastric, ovarian, breast, pancreatic, and primary hepatocellular carcinoma (HCC)." (PMID 33302959, 2020). "Cathepsin-facilitated invasion of BMI1-high hepatocellular carcinoma cells drives bile duct tumor thrombi formation." (PMID 40943452, 2025). "Previous reports have indicated that BMI-1 is overexpressed in gastric, ovarian, breast, head and neck, pancreatic, and radiation-induced lung cancers, as well as in primary hepatocellular carcinoma (HCC) and endometrial carcinoma." (PMID 38515119, 2024). "It has been found that the overexpression of BMI-1 promotes invasion and metastasis in pancreatic and hepatocellular cancers." (PMID 36497428, 2022). "A follow-up study demonstrated that knockdown of BMI1 increased sensitivity to 5-FU treatment in hepatocellular carcinoma." (PMID 34442383, 2021). "BMI1 stimulates CSC self-renewal in hepatocellular carcinoma, pancreatic cancer, and head and neck squamous cell carcinoma." (PMID 33499351, 2021). "The most active compound, wallichoside, decreased BMI1 protein levels in colon carcinoma cells and reduced the self-renewing capacity of human hepatocellular carcinoma cells." (PMID 33804165, 2021). "Bmi1 stimulates CSC self-renewal in hepatocellular carcinomas, pancreatic cancer, and head and neck squamous cell carcinomas." (PMID 29163356, 2017). "Bmi1 stimulates the proliferation of hepatocellular carcinomas by suppressing INK4A/ARF gene expression." (PMID 29163356, 2017). "Here, we show that perturbation of Bmi1 expression by using short hairpin RNA can inhibit the tumorigenicity and tumor growth of hepatocellular carcinoma cells both in vitro and in vivo." (PMID 25372945, 2014). "In the prognostic classification model, BMI1 is a member of the polycomb protein family, acts as an oncogene in the carcinogenesis of hepatocellular carcinoma in an independent manner of INK4a/ARF loci, and has been proved to be a qualified therapeutic target for HCC." (PMID 37470852, 2023). "In studies on liver disease, BMI1 was found to be highly expressed in hepatocellular carcinoma." (PMID 34442383, 2021). "It has been found that the proto-oncogene Bmi1 is highly expressed in hepatocellular carcinoma." (PMID 28472122, 2017). "The knockdown of BMI1 could critically inhibit the growth of hepatocellular carcinoma cells." (PMID 35261819, 2022). "A separate study demonstrated that the drug resistance of hepatocellular carcinoma can be overcome through eliminating HCC CSCs by codelivering Bmi1 siRNA with cisplatin in cationic nanoparticles." (PMID 34959397, 2021). "In addition, the BMI1 RNA transcript can be targeted directly; molecules targeting the transcript have shown promising therapeutic potential in reducing the oncogenic potential of prostate CSCs and hepatocellular carcinoma and liver CSCs." (PMID 33804165, 2021). "EZH2, a histone methyltransferase, has been shown to involve in cancer development and progression via epigenetic regulation of tumor suppressor microRNAs, whereas BMI1, a driver of hepatocellular carcinoma (HCC), is a downstream target of these microRNAs." (PMID 33168810, 2020). "This study aims to investigate the biological function of microRNA-200b and BMI1, predicted target of microRNA-200b in human hepatocellular carcinoma (HCC)." (PMID 26919246, 2016). "Our findings verify Bmi1 as a qualified treatment target for hepatocellular carcinoma (HCC) and support Bmi1 targeting treatment with chemotherapeutic agents." (PMID 25372945, 2014).
hepatocellular carcinoma (continued). "BMI1 downregulates PTEN expression in nasopharyngeal cancers and increases the proliferation of hepatocellular carcinomas." (PMID 33499351, 2021). "Since TET1-CD can induce genome-wide DNA demethylation, it is possible that oncogenes such as C-myc, Bmi1, EMS1, Kpna2 and c-fos in hepatocellular carcinoma epigenetics are also activated so as to weaken TET1-CD anticancer activity." (PMID 30551127, 2018). "Moreover, co-expression of Bmi-1 and RasV12 promotes hepatocellular carcinoma (HCC) formation in mice, and the induced muring tumors resemble human HCC." (PMID 23383216, 2013). "Bmi1 and DKK1 are highly expressed in liver samples taken by biopsy from patients with hepatitis B virus‐related hepatocellular carcinoma (HCC), but the effect of both Bmi1 and DKK1 on the carcinogenesis of adult hepatic stem cells (oval cells) has not previously been reported." (PMID 33639034, 2021). "Although imHC possess the Bmi-1 oncogene, which is absent from primary hepatocytes, its cell proliferation and apoptosis rates were not as aberrantly high as in the hepatoma cell lines." (PMID 33216752, 2020). "In hepatocellular carcinoma (HCC), SNHG3 regulates proliferation and migration through the SNHG3/miR-139-5p/BMI1 axis." (PMID 39349640, 2024). "Additionally, it was also demonstrated that silencing BMI1 could alleviate DDP resistance in many cancers, such as hepatocellular carcinoma and squamous cell carcinoma in the head and neck." (PMID 32581651, 2020). "However, whether Bmi1 can be used as a potential target for hepatocellular carcinoma treatment has not been fully confirmed yet." (PMID 25372945, 2014). "Multiple studies have reported that BMI1 controls hematopoietic stem cell (HSC) self-renewal, induces epithelial cell proliferation and modulates malignant behaviours in various types of cancers, including hepatocellular carcinoma (HCC) via Wnt/β-catenin pathway." (PMID 36497115, 2022).